ENSG00000228144 (novel protein)
Gene: Protein-coding gene on chromosome 12 (66,123,917 to 66,169,985, reverse strand). Ensembl gene ENSG00000228144.
Genetic constraint (gnomAD): Missense variants: 80 observed, 68.64 expected, observed/expected ratio (o/e) 1.17, 90% interval 0.97 to 1.4. Synonymous variants: 38 observed, 29.08 expected, observed/expected ratio (o/e) 1.31, 90% interval 1.01 to 1.71.